H19 (H19 imprinted maternally expressed transcript)
Diseases named in the same sentence as H19 in open-access papers (continued):
Sharing a sentence is not in itself a finding about the gene and the disease.
gastric cancer (continued). "This study aimed to examine associations of lncRNA ANRIL (rs17694493, rs1333045, rs1011970), H19 (rs217727), MALAT1 (rs3200401), MEG3 (rs1054000), and HOTAIR (rs17840857) polymorphisms with gastric cancer and atrophic gastritis in European population." (PMID 33333725, 2020). "In gastric cancer (GC), H19 had a high diagnostic ability with an AUC of 0.838." (PMID 33330574, 2020). "This study aimed to assess the associations of lncRNA ANRIL, H19, MALAT1, MEG3, HOTAIR single-nucleotide polymorphisms (SNPs) with gastric cancer and atrophic gastritis." (PMID 33333725, 2020). "In summary, we uncovered the prognostic value of COL3A1/FBN1/COL5A2/SPARC-mir-29a-3p-H19 ceRNA network in gastric cancer." (PMID 32742441, 2020). "The aim of this study was to investigate the role of long non-coding RNA (lncRNA) H19 in gastric cancer (GC) with Helicobacter pylori (H. pylori)." (PMID 31787851, 2019). "H19 is also shown to be overexpressed in gastric cancer tissues, with increased expression of H19 relating to advanced pathological tumor stage and pathological tumor node metastasis stage." (PMID 31299871, 2019). "It has been shown that the expression of lncRNA H19 was abnormal in the blood of patients with gastric cancer." (PMID 29599647, 2018). "H19 has been characterized as an oncogenic lncRNA and shown to be overexpressed in four gastric cancer cell lines (AGS1, MGC803, SGC7901, and MKN45)." (PMID 29719612, 2018). "For example, LncRNA H19 expression was up-regulated and closely related to TNM cancer stages in patients with gastric cancer, which can serve as a potential non-invasive diagnostic biomarker in gastric cancer." (PMID 29899709, 2018). "MiR-141 was shown to bind H19 in gastric cancer, and suppress H19 expression and its tumor-promoting functions." (PMID 29147648, 2017). "The top 4 predicted gastric cancer-related lncRNAs, H19, HOTAIR, MEG3, and PVT1 were confirmed by the updates of the LncRNADisease database." (PMID 28963512, 2017). "Several studies confirmed aberrant expression of circulating lncRNA H19 in the plasma of patients with gastric cancer compared with healthy controls." (PMID 28781594, 2017). "LncRNA H19 was significantly up-regulated in the plasma of Gastric Cancer (GC) patients, and could be a potential non-invasive diagnostic biomarker in GC." (PMID 28658310, 2017). "Expression of miR-141 was also found to be negatively correlated to that of lncRNA H19 (H19, imprinted maternally expressed transcript) in gastric cancer." (PMID 29147648, 2017). "Elevated expression profiles of H19 have been determined in plasma samples of gastric cancer patients." (PMID 28634418, 2017). "For example, circulating levels of lncRNA H19 are elevated in patients with gastric cancer compared with healthy controls and plasma H19 lncRNA expression was reduced postoperatively in patients with elevated levels of H19 lncRNA pre-operatively." (PMID 27358717, 2016).
gastric cancer (continued). "H19 and its mature product miR-675 enhanced the proliferation and invasion of gastric cancer AGS cells by activation of Akt/mTOR pathway, in which tumor suppressor RUNX1 served as a pivotal mediator." (PMID 27738631, 2016). "The H19/miR-675 signaling axis has been found to promote progression of different cancers, including colorectal cancer, gastric cancer, glioma, and prostate cancer." (PMID 26198047, 2016). "H19 has been shown to promote the proliferation and metastasis of bladder cancer, as the derivative of H19, miR-675 also abnormally enhanced cancer cell proliferation, like gastric cancer, glioma, and colorectal cancer." (PMID 26198047, 2016). "Plasma H19 levels in patients with gastric cancer are significantly higher than those in healthy controls." (PMID 26788991, 2016). "H19 is capable of regulating the progression of gastric cancer through the H19/miR-675/runt-related transcription factor 1 (RUNX1) signaling axis." (PMID 27464701, 2016). "It was reported that the overexpression of H19 is often correlated with poor prognosis in gastric cancer, bladder cancer, and lung cancer." (PMID 27626436, 2016). "H19 expression is significantly elevated in gastric cancer tissues compared with paracancerous tissues." (PMID 27464701, 2016). "H19 was upregulated in several different tumors, including esophageal cancer, gastric cancer, and breast cancer." (PMID 27672656, 2016). "DE lncRNA, H19 is also said to be involved in various other cancer types such as bladder cancer, cervical cancer, colon cancer, gastric cancer, kidney cancer, liver cancer, lung cancer and ovarian cancers (Reported in LncRNADisease database)." (PMID 30159409, 2016). "Remarkably, two lncRNAs, H19 and colon cancer associated transcript 1 (CCAT1) are transcriptionally activated by c-Myc in gastric cancer." (PMID 26788991, 2016). "Conversely, transcriptional activation of oncogenic lncRNAs are directly mediated by MYC, such as CCAT-1 in colon cancer and H19 in gastric cancer." (PMID 27340923, 2016). "H19's high expression level enforces the oncogenic progress of gastric cancer cells; while in hepatocellular carcinoma (HCC), it is recognized as tumor suppressor." (PMID 26788991, 2016). "LncRNA H19 has been shown to function as precursor of miR-675 and act as an oncogene in a variety of cancers, including bladder cancer, gastric cancer, glioma, and colorectal cancer." (PMID 27486980, 2016). "The effect of H19 in gastric cancer is mediated by the direct upregulation of ISM1 and the indirect suppression of CALN1 expression via miR-675." (PMID 26376677, 2015). "At the same time, H19/miR-675 upregulation promotes proliferation, migration and invasion in gastric cancer cells, and tumorigenesis and metastasis in in vivo gastric cancer models." (PMID 26379360, 2015). "H19 has been reported as being upregulated in gastric cancer cells and gastric cancer tissue samples compared to controls." (PMID 26379360, 2015). "H19 is a precursor of miR-675-5p/miR-675-3p, and H19-derived miR-675 has been reported to promote tumorigenesis of several cancers including colon and gastric cancers." (PMID 26353930, 2015). "Previous studies demonstrated that H19 was highly up-regulated in a variety of tumors, including liver, lung, esophageal, bladder and gastric cancers." (PMID 25944697, 2015). "A previous study indicated that the effect of H19 on gastric cancer was mediated by direct up-regulation of ISM1, which is a binding protein of H19." (PMID 25944697, 2015). "Overexpression of H19 appears to be important in the development of breast cacer, liver cancer, lung cancer, gastric cancer, esophageal and colorectal cancer cells." (PMID 26513297, 2015).
gastric cancer (continued). "HOTAIR, GCAT1 (gastric cancer-associated transcript 1), H19, and SUMO1P3 (small ubiquitin-like modifier SUMO 1 pseudogene 3) are the main lncRNAS reported as overexpressed in gastric carcinomas." (PMID 26448935, 2015). "Our results showing that H19 and miR-675 have different targets suggest that they play different roles during gastric cancer development and that they act through different pathways." (PMID 24810858, 2014). "Contrary to H19, uc001lsz expression level in gastric cancer tissues was found to be markedly lower." (PMID 24063685, 2013). "The most up-regulated lncRNAs in gastric cancer tissues were H19, HMlincRNA717, AI769947, BQ213083, AK054978, and DB077273." (PMID 24063685, 2013). "In this study, we have shown that LOI of the LIT1, IGF2 and H19 are present in 54.6%, 45% and 8.6% of gastric cancer tissues in Chinese patients respectively." (PMID 19737423, 2009). "The positive rate of LIT1, IGF2 and H19 LOI of gastric cancer tissues were 54.6% (12/22), 45% (18/40) and 8.6% (3/32) in Chinese patients." (PMID 19737423, 2009). "We further investigated whether H19 expression correlated with the outcome of gastric cancer patients." (PMID 38902391, 2024). "The lncRNA H19 and its mature product, miR-675, increase AKT/mTOR signaling in gastric cancer through the lncRNA-H19/miR-675/RUNX1 axis, whereas in gallbladder cancer, the same lncRNA can act as an endogenous competing RNA (ecRNA) by decoying miR-294-5p to increase AKT expression." (PMID 39614261, 2024). "Although lncRNA H19 is abundantly expressed in gastric cancer and functions as a pro-oncogene, it remains unclear whether lncRNA H19 contributes to the oncogenic process of H. pylori CagA." (PMID 38902391, 2024). "Curcumin targets H19 in gastric cancer cells and Malat1 in colon cancer cells." (PMID 37796408, 2023). "In addition, H19 has been shown to promote glycolysis in gastric cancer (GC) and oral cancer cells, thereby enhancing the Warburg effect and promoting the metastatic potential." (PMID 37384249, 2023). "Other lncRNAs are under study as potential biomarkers for diagnosis of other cancers, such as lncRNA LINC00152 for hepatocellular carcinoma, lncRNA H19 for gastric cancer, lncRNA UCA1 for bladder cancer and oral squamous cell carcinoma, MEG 3 for multiple myeloma, etc.." (PMID 37143733, 2023). "Furthermore, in a mouse model injected intravenously with gastric cancer cells, metformin suppressed metastasis in a similar way to that of mice that were injected with H19-knockdown cells." (PMID 38004379, 2023). "Moreover, we screened lncRNAs related to the pathogenesis of gastric cancer and tried to investigate the effect of the H19/miR-204-5p/NF-κB axis in TP/TNF-α–induced apoptosis in gastric carcinoma." (PMID 36110523, 2022). "Moreover, HULC, H19, HOTAIR and GACAT2 (for “gastric cancer-associated transcript 2”) were found to be significantly increased in the plasma of gastric cancer (GC) patients compared to healthy individuals." (PMID 35729321, 2022). "Meanwhile, the expression level of H19 increased with the grade of gastric cancer." (PMID 36246567, 2022). "This implies that diagnosis based on the quantification of plasmatic levels of H19 or GACAT2 may potentially result in a significant number of false-positive results when testing for gastric cancer." (PMID 35729321, 2022). "lncRNA-H19, a transcriptional product of the maternally expressed and paternally imprinted gene H19, was initially recognized as an oncogene in the progression of diverse tumors, including glioblastoma, bladder, and gastric cancer." (PMID 35178162, 2022). "Furthermore, studies have shown that H19 and miR-675 are significantly upregulated in gastric cancer cells and tissues." (PMID 35674441, 2022).
gastric cancer (continued). "Therefore, we chose lncRNA H19 for further investigation of function in resveratrol‐treated gastric cancer cells." (PMID 35166018, 2022). "H19 may play a role in promoting the invasion and migration of gastric cancer cells as a precursor of miR-675." (PMID 36246567, 2022). "To further validate the biological function of H19 as a ceRNA, we explored whether modulating H19/miRNA regulation affects the characteristics of gastric cancer cells." (PMID 36090894, 2022). "Then, we intersected the prediction results with the downregulated genes in H19-high tissues compared with H19-low tissues and obtained the potential genes that are affected by the overexpression of H19 in gastric cancer tissues through its action as a miRNA sponge." (PMID 36090894, 2022). "LncRNA H19 was recognized as the oncogene of gastric cancer." (PMID 36110523, 2022). "In gastric cancer, H19 is overexpressed and plays an important role in apoptosis." (PMID 34977037, 2021). "The relationship between H19 and miR-200 is more complex: in gastric cancer cells, miR-141 and H19 were shown to compete with each other for mRNA targets, whereas in HCC, H19 upregulates miR-200 family expression through a mechanism involving increased histone acetylation." (PMID 34884985, 2021). "Additionally, curcumin can also reduce the expression of oncogene c-Myc which indicate that curcumin inhibits the proliferation of gastric cancer cells by down-regulating the c-Myc/lncRNA H19 pathway." (PMID 33912467, 2021). "Furthermore, mechanism studies have shown that curcumin can inhibit the growth of gastric cancer cells by down-regulating lncRNA H19 which was proved to be a oncomir." (PMID 33912467, 2021). "Additionally, H19 was demonstrated to promote gastric cancer cells to proliferate and invade through the miR-138/E2F2 axis." (PMID 34295816, 2021). "H19 positively correlates with miR-675 expression in gastric cancer." (PMID 34977037, 2021). "Previous studies have shown that H19 promotes cancer development through different mechanisms, as examples: in gastric cancer through Fas-related protein, in cholangiocarcinoma through IL-6 and CXCR4, in colorectal cancer through HMGA1, and in multiple myeloma through P50/P65." (PMID 34843522, 2021). "Moreover, additional studies also supported that lncRNA (H19, LINC00152, UC001lsz) and lncRNA MALATl high expression was related to the increased risk of gastric cancer." (PMID 33473276, 2021). "Likewise, gastric cancer patients with high H19 expression had a shorter recurrence-free survival in GSE26253 microarray data from GEO databases." (PMID 34977037, 2021). "Meanwhile, a genotype analysis of four H19 SNPs (rs217727 C>T, rs2839698 C>T, rs3741216 A>T, rs3741219 T>C) in 500 patients with gastric cancer and 500 healthy controls showed that the rs217727T and rs2839698T allele carriers have increased risk of developing gastric cancer." (PMID 33236528, 2021). "Furthermore, the oncogene c-Myc was shown to directly induce H19 expression by binding to the H19 promoter, and thereby promoting proliferation of gastric cancer cells." (PMID 34680593, 2021). "Moreover, overexpression of lncRNA H19 has been determined to enhance the proliferation, invasion of gastric cancer and contributed to poor prognosis in GC patients in multiple studies 46-49." (PMID 32742441, 2020).
gastric cancer (continued). "Though a growing number of long noncoding RNAs (lncRNAs), including HOTAIR, MEG3, MALAT1, H19, GAPLINC, and GClnc1, have been reported to be associated with gastric cancer tumorigenesis, the role of lncRNAs in human gastric cancer and their prognostic value are still inadequately explored." (PMID 32117443, 2020). "Furthermore, H19 has been shown to promote gastric cancer cell proliferation, invasion and metastasis through various mechanisms." (PMID 33333725, 2020). "For example, H19 exhibits carcinogenic effects in gastric cancer." (PMID 32695786, 2020). "We were not able to determine significant associations with H19 SNPs and atrophic gastritis or gastric cancer." (PMID 33333725, 2020). "To date, several lncRNAs, including RMRP, AA174084, PVT1, H19, LINC00982, ABHD11-AS1 (ABHD11 antisense RNA 1), UCA1 (urothelial cancer associated 1), and LINC00152 have been identified from gastric juice and demonstrated as biomarkers for gastric cancer." (PMID 32460771, 2020). "LncRNA H19, which is a maternally expressed gene, is overexpressed in multiple types of cancer, including glioma, bladder cancer, gastric cancer, pancreatic cancer, and cervical cancer, and it plays a role in proliferation, immigration, invasion and angiogenesis." (PMID 30948500, 2019). "In gastric cancer, lncRNA H19 promotes cell proliferation and inhibits cell apoptosis." (PMID 29308050, 2018). "For instance, in gastric cancer, H19-miR-675 regulates cell proliferation by repressing RUNX1." (PMID 29579063, 2018). "Competing endogenous activity of H19 identified in this study suggests that overexpression of H19 and miR-148a downregulation could be a signature for gastric cancer." (PMID 29719612, 2018). "Furthermore, high expression of H19 was positively associated with advanced TNM stage and was a predictor of overall survival (OS) in gastric cancer patients." (PMID 30071841, 2018). "For example, H19 was found to be significantly up-regulated in plasma of gastric cancer patients, and could be used to discriminate gastric cancer patients from healthy controls." (PMID 29559565, 2018). "In addition, diagnostic performances of lncRNAs TINCR, CCAT2, AOC4P, BANCR, LINC00857, AA174084, and H19 were evaluated in body fluid samples (e.g., plasma and gastric juice) of gastric cancer patients." (PMID 28634418, 2017). "Thus, H19 promotes epithelial-mesenchymal transition in gastric cancer and is a potential therapeutic target." (PMID 29088808, 2017). "The plasma level of H19 is higher in patients with gastric cancer compared to normal controls." (PMID 29099749, 2017). "Recent studies also indicated that H19 could enhance carcinogenesis and metastasis of gastric cancer through the direct upregulation of ISM1 and the indirect suppression of CALN1 expression." (PMID 27517318, 2016). "Moreover, in gastric cancer, H19 expression was significantly related to histological grade (OR = 0.50, 95% CI = 0.29–0.86, P = 0.01), TNM stage (OR = 0.19, 95% CI = 0.11–0.33, P < 0.01), and tumor invasion depth (OR = 0.11, 95% CI = 0.04–0.27, P < 0.01)." (PMID 27672656, 2016). "Besides, H19 can enhance carcinogenesis and metastasis in gastric cancer via miR-675 and calneuron 1(CALN1)." (PMID 27429196, 2016). "In addition, progressive up-regulation of lncRNA H19 was found in advanced stages of gastric cancer, and circulating lncRNA H19 has been suggested as a potential novel biomarker in gastric cancer." (PMID 27486980, 2016). "Up-regulated long non-coding RNA H19 contributes to proliferation of gastric cancer cells." (PMID 26376677, 2015).